NR1D2 (nuclear receptor subfamily 1 group D member 2)
Diseases named in the same sentence as NR1D2 in open-access papers (continued):
Sharing a sentence is not in itself a finding about the gene and the disease.
gastric cancer (1 paper, 2024). A primary or metastatic malignant neoplasm involving the stomach. "The mRNA expression of both nuclear receptor subfamily 1 group D member 1 (NR1D1) and nuclear receptor subfamily 1 group D member 2 (NR1D2) is elevated in gastric cancer compared to normal tissue." (PMID 39062777, 2024). "NR1D1 and NR1D2 are transcription factors that bind ROREs and act as transcriptional repressors to inhibit the expression of BMAL1:CLOCK, underlining the importance of considering circadian rhythms in gastric cancer development and treatment." (PMID 39062777, 2024).
Hepatic steatosis (1 paper, 2023). Steatosis is a term used to denote lipid accumulation within hepatocytes. "Meanwhile, the significant five-fold repression of nuclear receptor NR1D2/Rev-Erbß has major implications for metabolic homeostasis; its depletion represses expression of genes coding for metabolic enzymes and causes marked hepatic steatosis in mice." (PMID 36674967, 2023).
melanoma (1 paper, 2022). A malignant, usually aggressive tumor composed of atypical, neoplastic melanocytes. "In melanoma, lncRNA LINC01224 was reported to upregulate radioresistance via miR-193a-5p/NR1D2 axis." (PMID 35600868, 2022).
mucopolysaccharidosis type 2 (1 paper, 2013). A lysosomal storage disease leading to a massive accumulation of glycosaminoglycans and a wide variety of symptoms including distinctive coarse facial features, short stature, cardio-respiratory involvement and skeletal abnormalities. "After 24 hours of treatment with idursulfase in fibroblasts of patients with Mucopolysaccharidosis type II the expression evaluated by NGS of the genes CLOCK, ARNTL2, NR1D1, NR1D2, and TIMELESS showed higher expression levels compared to untreated HS fibroblasts." (PMID 24083598, 2013).
opioid use disorder (1 paper, 2024). A substance-related disorder that involves the recurring use of opioids despite negative consequences. "Similarly, NR1D2, BMAL1, and CSNK1D rhythms were disrupted in opioid use disorder (OUD) and AUD patients compared to controls." (PMID 39766481, 2024).
ovarian carcinoma (1 paper, 2020). A malignant neoplasm originating from the surface ovarian epithelium. "Considering the age of the patient at the initial pathologic diagnosis, 18 competing triplets are found to be associated with the overall survival time of patients in ovarian cancer, including miR-224-5p/AL354892.2/ZBTB12, miR-3653-3p/FGD5-AS1/NR1D2, miR-224-5p/AC112491.1/NDUFB8, and so on." (PMID 33519912, 2020).
paroxysmal AF (1 paper, 2021). "The expression of BMAL1, CRY2, NR1D2, PER2, and RORA was significantly lower in patients with persistent AF than in those with paroxysmal AF (persistent AF vs. paroxysmal AF, all p < 0.05)." (PMID 33430447, 2021).
preeclampsia (1 paper, 2022). Preeclampsia is a hypertensive disorder of pregnancy that is characterized by new-onset hypertension with proteinuria presenting after 20 weeks of gestation, and depending on mild or severe forms may initially present with severe headache, visual disturbances, and hyperreflexia. "Further, in our recent study, we found that the placenta from women with preeclampsia presented with increased CRY1 mRNA as well as reduced NR1D2 and PER3 mRNA." (PMID 36712876, 2022).
retinal degeneration (1 paper, 2025). Degeneration of the retina. "As expected, these include clock genes such as Cry1 and Nfil3 (up) and Per3 and Nr1d2 (down) but also a few other genes, notably linked to retinal degeneration such as Myo7A61 that was substantially downregulated, or Loxl4 and Ppard that were highly upregulated." (PMID 40171795, 2025).
sarcopenia (1 paper, 2025). Progressive decline in muscle mass due to aging which results in decreased functional capacity of muscles. "However, the causality of the association between the circadian timing system of the liver and sarcopenia variables was not demonstrated, and the effects included both gene upregulation (Per, Cry, Nr1d1, Nr1d2, and Dbp) and downregulation (Bmal1 and Npas2)." (PMID 39747789, 2025).
Sepsis (1 paper, 2024). Sepsis is defined as life-threatening organ dysfunction caused by a dysregulated host response to infection. "In a study on circadian rhythms in patients with sepsis, it was suggested that sepsis suppresses the expression of the Circadian gene, such as CRY1, REV-ERBα, NR1D2, DBP, and PER2." (PMID 39097582, 2024).
Shock (1 paper, 2021). The state in which profound and widespread reduction of effective tissue perfusion leads first to reversible, and then if prolonged, to irreversible cellular injury. "Additionally, we found that NR1D1, NR1D2, CRY1, CRY2, PER1, PER2 and DBP had altered rhythms in at least some patients with septic shock." (PMID 33900485, 2021).
skin cutaneous melanoma (1 paper, 2023). "Similar associations were found for the overall survival (OS), where significantly higher expression levels of NR1D2 and BMAL1 were associated with longer survival among skin cutaneous melanoma patients." (PMID 37373286, 2023).
cancer (27 papers, 2009 to 2026). A tumor composed of atypical neoplastic, often pleomorphic cells that invade other tissues. "NR1D2 has also been implicated in autophagy regulation, a highly conserved cellular process with a dual role in cancer, as it is involved in preventing tumour development in the early stages, as opposed to maintenance and metabolic adaptation in established tumours and metastasis." (PMID 40564218, 2025). "However, whereas NR1D2 is the major variant in various human cancer cells, NR1D1 is more abundant in normal tissues." (PMID 34440171, 2021). "We highlight recent discoveries including BRCA1-dependent ubiquitination of GPX4 and its implications for PARP inhibitor synthetic lethality, NR1D2-mediated transcriptional repression of FSP1, and stromal protection conferred by cancer-associated fibroblasts." (PMID 42231453, 2026). "Originally known as a transcriptional repressor in circadian rhythm, the nuclear receptor NR1D2 has recently been found overexpressed in a variety of cancers." (PMID 41567216, 2025). "The key difference between the core clock in these cancers and healthy tissue was a significant delay in the peak expression times of core clock genes NR1D2, PER2, TEF and DEC1." (PMID 40424435, 2025). "These analyses identified several cancer-related genes, including Kif26a, Acer2, Serpine1, Nr1d2, Efnb2, and Chst11, to be affected by ECS exposure." (PMID 39273313, 2024). "NR1D2 is a transcriptional repressor that has been implicated in the epithelial–mesenchymal transition (EMT), a process that is crucial for cancer metastasis." (PMID 37711170, 2023). "However, more studies are needed to determine the mechanism by which NR1D2 regulates stem character in this type of cancer." (PMID 40564218, 2025). "NR1D2 could regulate stemness in cancer, probably through the regulation of glucose and lipid metabolism." (PMID 40564218, 2025). "NR1D2 (nuclear receptor subfamily 1 group D member 2) acts as a transcription inhibitor and may affect cancer carbohydrate and lipid metabolism." (PMID 35600868, 2022). "NR1D2 is also overexpressed in some cancers, where it is important for focal adhesion formation." (PMID 35421924, 2022). "This discordance between NR1D1 and NR1D2 is a possible source of the small amplitudes in RRE-targets NPAS2, NFIL3, and CRY1 in the cancers." (PMID 40424435, 2025). "Therefore, this could be a mechanism of metabolic regulation by NR1D2 in cancer." (PMID 40564218, 2025). "Among 7912 samples across 18 cancer types, we interestingly observed that the majority of the clock control gene, such as HLF, KLF10, FBXL3, TEF, RORs (RORA, RORB, RORC), and NR1D2, are down-regulated in a wide range of cancers." (PMID 36895015, 2023). "In several types of cancer, NR1D2 regulates cancer progression and relapse through cancer stem cells (CSCs), although this aspect has not been studied in CRC." (PMID 40564218, 2025). "Besides, the roles of seven genes (NR1D2, TANK, LRSAM1, PLXNA1, INHBE, HDGF, and ARAF) in SCLC have not been reported, however those genes have been reported to play a vital role in other type cancer." (PMID 34741430, 2021). "In order to achieve a systematic understanding of circadian clock in cancer, we define a core subset of clock family genes including 7 positive regulators (CLOCK, NPAS2, ARNTL, ARNTL2, RORA, RORB, and RORC) and 7 negative regulators (PER1, PER2, PER3, CRY1, CRY2, NR1D1, and NR1D2)." (PMID 31708917, 2019). "Among 716 samples across 29 cancer types, we interestingly observe that most of the negative regulators, such as PER1, PER2, PER3, CRY1, CRY2, and NR1D2, are down-regulated in a wide range of cancers." (PMID 31708917, 2019). "The two datasets with the highest ΔCCD (>50% higher than any ΔCCD we observed in human cancer) were those in which the knockout mice lacked not one, but two components of the clock (Cry1 and Cry2 in GSE13093; Nr1d1 and Nr1d2 in GSE34018)." (PMID 29404219, 2018).
tumor (17 papers, 2015 to 2026). "The results showed a greater accumulation of early‐Tex in tumor tissues with pathological complete response to neoCRT, suggesting that NR1D2+ Tex is associated with better clinical outcomes in LARC." (PMID 41190765, 2026). "Consequently, the validation of NR1D2 in vivo loss-of-function becomes essential for a better understanding of its potential as a therapeutic target and its association with tumor progression." (PMID 39516282, 2024). "Functional analysis identified NR1D2 as a key gene promoting tumor migration through cellular senescence." (PMID 41567216, 2025). "Transwell and wound healing assays consistently demonstrated that NR1D2 promotes tumor migration by inducing cellular senescence and enhancing the secretion of SASP-related factors." (PMID 41567216, 2025). "Western blot analysis of 15 paired patient samples further confirmed the down-regulation of NR1D2 in tumor tissues relative to adjacent normal tissues, with consistent GAPDH expression validating experimental reliability (P < 0.001)." (PMID 41562084, 2025). "Functional assays indicated that NR1D2 facilitated malignant progression by regulating macrophage polarization and enhancing tumor cell migration." (PMID 41562084, 2025). "Together, our study unveils a novel mechanism by which hormone inhibition promotes tumor malignancy, and describes an evolutionarily conserved role of the oncogene E75/NR1D2 in integration of Hippo and Notch pathway activity during tumor progression." (PMID 39516282, 2024). "We identified a high expression of NR1D2 in the tumour as an independent prognostic factor for LR development." (PMID 34440171, 2021). "We observed that core clock genes, PERs, CRY2, CLOCK, NR1D2, RORA and RORB exhibited global patterns of somatic loss and downregulation across multiple tumour types." (PMID 31014368, 2019). "Therefore, to analyse the influence of the circadian gene NR1D2 in tumour progression in depth, it is necessary to build more complex research models than those used in this study, such as 3D models, organoids from patients or transgenic animals." (PMID 40564218, 2025). "In the SWI/SNF-mutant cohort, a seven-gene signature comprising CRIM1 (angiogenesis), VEGFC (lymphangiogenesis), BMP7 (tumor microenvironment regulation), NR1D2 (immune modulation), BMPR1B (tumor proliferation), CR2 (B-cell activation), and TAPBPL (antigen presentation) was ultimately retained." (PMID 41438758, 2025). "In addition, we analysed the expression of NR1D2 in a cohort of patients and determined its relationship with the characteristics of patients and tumours." (PMID 40564218, 2025). "Further investigation of the in vivo functions of NR1D2 using knock-out mice across various tumor types could be particularly insightful and advance the discovery of novel therapeutic strategies for both hormone-dependent and hormone-independent tumors." (PMID 39516282, 2024). "Similarly to CRY1, although the expression of NR1D2 was reduced in tumour tissue compared to normal mucosa, patients with a higher expression of this protein also had an increased risk of developing LR." (PMID 34440171, 2021).
tumor (continued). "Finally, we examined the impact of disrupting NR1D2 on GSC-driven tumor growth in vivo." (PMID 39516282, 2024). "Other studies have revealed that NR1D2 plays a role in regulating the Hippo and Notch pathways which seems to be crucial for GSC-induced tumour growth." (PMID 40564218, 2025). "NR1D2 is downregulated in LUSC and promotes tumor progression through macrophage polarization and enhanced migration." (PMID 41562084, 2025). "Consistent with the elevation of NR1D2 expression in the GSCs, we found that the depletion of NR1D2 inhibits GSC proliferation and improves the survival of tumor-bearing mice." (PMID 39516282, 2024). "Collectively, these results indicate that NR1D2 plays a conserved role in regulating the Hippo and Notch pathways and is crucial for GSC-induced tumor growth in vivo." (PMID 39516282, 2024). "To examine whether SASP factor secretion influences tumor development, we cultured normal HCT15 cells in conditioned medium from NR1D2-knockdown cells." (PMID 41567216, 2025). "As a common complication of tumor, VTE may be closely related to immune genes CD3G and NR1D2." (PMID 33388092, 2021). "Likewise, although NR1D2 and PER3 do not show significant differece between tumor and normal tissues, they do show significant correlation with survival conditions." (PMID 39043735, 2024).
infection (4 papers, 2011 to 2022). The state of being infected such as from the introduction of a foreign agent such as serum, vaccine, antigenic substance or organism. "Infection efficiency was near 100%, and we found that the adenovirus induced Cre expression results in a 94% reduction of Nr1d1 and an 87% reduction of Nr1d2 in the ad-Cre-GFP infected CFs." (PMID 36386186, 2022). "The levels of the Rora, SPARC, PLG, G6PC, NR1D2 and AGRP mRNAs were measured by qRT-PCR 24 h, 48 h and 72 h after infection of HepG2 cells with either Ad-RORα or control Ad-GFP." (PMID 21818335, 2011). "In Cpn group, infection induced down-regulation of acetyl-Coenzyme A acyltransferase 2 (Acaa2, FC = 0.41), ELOVL family member 6, elongation of long chain fatty acids (Elovl6, FC = 0.44), and nuclear receptor subfamily 1, group D, member 2 (Nr1d2, FC = 0.44)." (PMID 24131481, 2013). "NR1D2-mediated PNPLA2/ATGL inhibition disrupts the lipid metabolism of macrophages in the human body, leading to lipid accumulation and weakening the effect of autophagy on Burkholderia pseudomallei immunity to infection, leading to the continued development of infection." (PMID 34925055, 2021).
cardiovascular diseases (2 papers, 2011 to 2023). "Previous studies have shown that the decrease of Nr1d1 and Nr1d2 leads to dysfunction of circadian rhythm and aggravates cardiovascular diseases." (PMID 37018396, 2023).
heart diseases (1 paper, 2025). "In 1994, researchers discovered a related orphan receptor with high homology to REV-ERBα, named NR1D2 or REV-ERBβ REV-ERBα/β proteins, essential components of the circadian clock, are widely expressed across tissues and have become key therapeutic targets for heart diseases." (PMID 40255337, 2025).
NR1D2 also shares sentences with these, for which no sentence is quoted: dyslipidemia (2 papers); type 2 diabetes (2); Alzheimer disease (1); cardiovascular malformations (1); Glucose intolerance (1); Hyperglycemia (1); hypertension (1); medulloblastoma (1); MODY (1); multiple sclerosis (1); polycystic ovary syndrome (1); prostate carcinoma (1); rheumatoid arthritis (1); schizophrenia (1); sleep disorder (1); small cell carcinoma (1); Stroke (1).